MRPL32 (mitochondrial ribosomal protein L32)
Description:
Component of the mitochondrial large ribosomal subunit (mt-LSU). The mitochondrial ribosome (mitoribosome) is a large ribonucleoprotein complex responsible for the synthesis of proteins inside mitochondria.
Synonyms: L32mt; MRP-L32; HSPC283; bMRP-59b; bL32m
Tractability: Small molecule: a structure with a bound ligand is known. PROTAC: ubiquitination databases record sites on it; its protein half-life has been measured.
Gene: Protein-coding gene on chromosome 7 (42,932,346 to 42,948,958, forward strand). Ensembl gene ENSG00000106591.
Subcellular location: Mitochondrion
Pathways (Reactome):
Metabolism of proteins: Mitochondrial protein degradation; Mitochondrial ribosome-associated quality control; Mitochondrial translation elongation; Mitochondrial translation initiation; Mitochondrial translation termination
Gene Ontology:
Molecular function: protein binding; RNA binding; structural constituent of ribosome
Biological process: mitochondrial translation; translation
Cellular component: mitochondrial large ribosomal subunit; mitochondrion; mitochondrial inner membrane; mitochondrial matrix; mitochondrial ribosome; large ribosomal subunit
Genetic constraint (gnomAD): Loss-of-function variants: 14 observed, 21.14 expected, observed/expected ratio (o/e) 0.66, 90% interval 0.44 to 1.03. The upper end of that interval is the gene's LOEUF score, 1.03, which puts it in group 4 of 6, group 1 being the genes least tolerant of losing a copy. Missense variants: 211 observed, 240.59 expected, observed/expected ratio (o/e) 0.88, 90% interval 0.78 to 0.98. Synonymous variants: 83 observed, 91.1 expected, observed/expected ratio (o/e) 0.91, 90% interval 0.76 to 1.09.
Homologues: Orthologues: chimpanzee MRPL32 (98% identical), macaque MRPL32 (95% identical), dog MRPL32 (81% identical), guinea pig MRPL32 (76% identical), mouse Mrpl32 (71% identical), rat Mrpl32 (71% identical), tropical clawed frog mrpl32 (52% identical), zebrafish mrpl32 (50% identical), Drosophila melanogaster mRpL32 (27% identical), Caenorhabditis elegans mrpl-32 (20% identical).
Diseases named in the same sentence as MRPL32 in open-access papers:
MRPL32 is named in the same sentence as 1 disease in open-access papers, as found by Europe PMC text mining. Sharing a sentence is not in itself a finding about the gene and the disease. The quoted sentences say what the papers report.
glioma (1 paper, 2024). A benign or malignant brain and spinal cord tumor that arises from glial cells (astrocytes, oligodendrocytes, ependymal cells). "Prior studies demonstrated that suppressing MRPL32 could reduce oxygen-glucose deprivation/reperfusion damage and that REXO2 was associated with a poorer prognosis in glioma." (PMID 38596213, 2024).